PAXX (PAXX non-homologous end joining factor )
Synonyms: C9orf142; XLS
Gene: Protein-coding gene on chromosome 9 (136,992,403 to 136,994,074, forward strand). Ensembl gene ENSG00000310560.
Gene Ontology:
Molecular function: DNA polymerase binding; molecular adaptor activity; protein binding; protein homodimerization activity
Biological process: DNA damage response; double-strand break repair via nonhomologous end joining
Cellular component: chromosome; cytoplasm; Ku70:Ku80 complex; nonhomologous end joining complex; nucleoplasm; nucleus; site of double-strand break
Homologues: Orthologues: chimpanzee PAXX (99% identical), macaque PAXX (97% identical), pig PAXX (83% identical), mouse Paxx (75% identical), dog PAXX (73% identical), guinea pig PAXX (70% identical), rat Paxx (63% identical), zebrafish paxx (27% identical).
Diseases named in the same sentence as PAXX in open-access papers:
PAXX is named in the same sentence as 19 diseases in open-access papers, as found by Europe PMC text mining. Sharing a sentence is not in itself a finding about the gene and the disease. The quoted sentences say what the papers report.
glioma (4 papers, 2018 to 2023). A benign or malignant brain and spinal cord tumor that arises from glial cells (astrocytes, oligodendrocytes, ependymal cells). "Our study found that PAXX deficiency improved TMZ potency in TMZ resistance glioma cells and this is likely due to participation of PAXX in a variety of DNA repair pathways." (PMID 30238427, 2018). "We observed that PAXX deficiency cause more sensitivity to TMZ-resistant glioma cells." (PMID 30238427, 2018). "We are also interested in whether PAXX participates in HR in glioma cells because HR can compete with NHEJ for and is usually upregulated when NHEJ is impaired." (PMID 30238427, 2018). "Our result indicates that PAXX participates in BER in glioma cells via interaction with pol β." (PMID 30238427, 2018). "To determine whether PAXX participates in DNA repair pathways in glioma cells, we first used CRISPR/Cas 9 method to generate PAXX-deficient cell lines." (PMID 30238427, 2018). "Therefore, inhibition of PAXX may provide a promising way to overcome TMZ resistance and improve TMZ therapeutic effects in glioma treatment." (PMID 30238427, 2018). "Therefore, we hypothesize that PAXX, which contributes to BER, as well as NHEJ efficiency, promotes TMZ resistance in glioma cells." (PMID 30238427, 2018).
colon carcinoma (3 papers, 2020 to 2024). "PAXX was observed to be negatively correlated with twenty different immune cells, thereby suggesting the association of PAXX expression with overall reduced tumor immune infiltration in colon cancer." (PMID 33195430, 2020). "In concordance to PAXX overexpression observed in colon tumors, higher expression of PAXX was associated with poor OS and DSS." (PMID 33195430, 2020). "Although, PAXX and XLF perform overlapping functions and XLF can efficiently compensate for PAXX deficiency in colon cancer cells, however, another study demonstrated that one protein between PAXX and XLF is essential for NHEJ repair, and PAXX also promotes Ku accumulation at DSBs." (PMID 33195430, 2020). "Studies have shown a connection between the expression level of PAXX and cancer development in human patients, and PAXX has been identified as an independent predictor of colon cancer." (PMID 38666838, 2024). "We conclude from these results that PAXX expression in colon cancer is at least partly under epigenetic control." (PMID 33195430, 2020). "As our results suggest the utility of PAXX as a potential therapeutic target in colon cancer, we performed gene set enrichment analysis to further determine the association of PAXX expression with underlying oncogenic pathways in colon cancer." (PMID 33195430, 2020). "This analysis revealed upregulation of XRCC5, PRKDC, and PAXX in colon cancer compared to normal colon tissues, while LIG4 and NHEJ1 (XLF) displayed downregulation." (PMID 33195430, 2020). "Given this information, it was of interest to investigate the role of epigenetic modifications in the overexpression of PAXX in colon tumors." (PMID 33195430, 2020). "Intriguingly, we observed that NHEJ1 expression is negatively correlated with PAXX expression, and PAXX was observed to be consistently overexpressed in colon tumors compared to the normal tissues, both at the mRNA and protein levels." (PMID 33195430, 2020). "Thus our study provides novel insights into NHEJ pathway status in colon cancer and suggests the potential utility of PAXX as a novel prognostic marker and a therapeutic target in colon cancer." (PMID 33195430, 2020). "Furthermore, PAXX expression exhibited a negative association with the abundance of immune cells in the colon tumor microenvironment, which suggests its association with reduced overall infiltration of immune cells in colon cancer." (PMID 33195430, 2020). "To determine the expression pattern of core NHEJ genes in colon cancer, we performed Oncomine analysis for XRCC6 (Ku70), XRCC5 (Ku80), PRKDC (DNA-PKcs), XRCC4 (XRCC4), LIG4 (DNA ligase 4), NHEJ1 (XLF), and PAXX (PAXX/XLS)." (PMID 33195430, 2020).
osteosarcoma (3 papers, 2023 to 2025). A usually aggressive malignant bone-forming mesenchymal neoplasm, predominantly affecting adolescents and young adults. "Thus, it suggests that PAXX may represent a promising novel target for overcoming chemoresistance in OS therapy, and PAXX deficiency has been observed to re-sensitize chemoresistant osteosarcoma cells to doxorubicin and cisplatin." (PMID 39333437, 2025). "However, the small molecule M11 disrupts PAXX-Ku70 binding and resensitizes chemoresistant osteosarcoma to doxorubicin and cisplatin." (PMID 39333437, 2025).
breast carcinoma (2 papers, 2020 to 2023). "To determine if LINP1 and PAXX compete for Ku in cells, we determined LINP1 localization in MDA-231 breast cancer cells using single-molecule RNA fluorescence in situ hybridization (FISH)." (PMID 33045735, 2020).
alveolar rhabdomyosarcoma (1 paper, 2025). A rapidly growing malignant mesenchymal neoplasm. "Other frequently altered genes are RB1 and MYC (a well-known oncosuppressor and oncogene, respectively), NF1 (known for being often mutated in neural tumors), and PAXX (often fused with FOXO1 in alveolar rhabdomyosarcomas)." (PMID 40725011, 2025).
cervical cancer (1 paper, 2024). A primary or metastatic malignant neoplasm involving the cervix. "In conclusion, the genes PAXX and KIF3B are associated with DNA repair and cell division, supporting the GSEA study’s findings that the high-risk subgroup may affect the long-term survival of cervical cancer by influencing DNA replication and the cell cycle." (PMID 38666838, 2024).
immune deficiency (1 paper, 2021). "These in vivo results reveal new functional interplays between XRCC4 and PAXX, ATM and Xlf in mouse development and provide new insights into the understanding of the clinical manifestations of human XRCC4-deficient condition, in particular its absence of immune deficiency." (PMID 34519267, 2021).
prostate carcinoma (1 paper, 2025). A carcinoma that arises from epithelial cells of the prostate gland. "The association between PAXX and prostate cancer has not been reported." (PMID 40442579, 2025).
cancer (4 papers, 2017 to 2024). A tumor composed of atypical neoplastic, often pleomorphic cells that invade other tissues. "While the precise reason for the strong dependence on PAXX in NHEJ in human cancer cell lines and the dispensable role of PAXX in mice in vivo is yet to be determined, species differences are unlikely to be the only explanation." (PMID 28051062, 2017). "Except rare truncating mutations in the C-terminal KU-binding region of PAXX, the PAXX (C9Orf142) gene is amplified and overexpressed in several human cancers (cBioPortal), suggesting that PAXX function might modulate the therapeutic responses to genotoxic cancer therapies, such as radiation." (PMID 28051062, 2017). "Although, these studies suggest that both PAXX and XLF perform overlapping but essential functions in NHEJ mediated DNA repair and influence drug resistance in solid tumors, the consequences and clinical implications of their altered expression in cancer patients have never been investigated." (PMID 33195430, 2020).
tumor (4 papers, 2017 to 2023). "Given the severe IR sensitivity observed in PAXX-depleted human tumour lines, patients with PAXX deficiencies have been expected." (PMID 28051062, 2017). "Furthermore, PAXX overexpression was also associated with several oncogenic pathways as well as a reduction in numbers of tumor-infiltrating lymphocytes." (PMID 33195430, 2020). "Surprisingly, different from what was predicted in mouse model, PAXX was found to be highly expressed in the TCGA colon cancer dataset due to the hypomethylation status of the PAXX gene promoter region in tumor cells." (PMID 35309348, 2022). "We further correlated PAXX expression with the computationally determined abundance of different tumor-infiltrating immune cells in TCGA-COAD dataset." (PMID 33195430, 2020). "PAXX was recently proposed to function as a NHEJ factor on the basis of its structural homology to XRCC4 and XLF, and the IR sensitivity of PAXX-depleted human tumour lines." (PMID 28051062, 2017). "One possibility is that PAXX may promote tumour suppression or prevent premature aging in long-living organisms." (PMID 28051062, 2017). "This analysis revealed significant upregulation of five genes, (XRCC6, XRCC4, PRKDC, XRCC4, and PAXX) and downregulation of two (LIG4 and NHEJ1) NHEJ pathway genes, in tumor tissues compared to the normal tissues." (PMID 33195430, 2020). "However, although PAXX itself does not seem to play a role in tumor suppression, it is still possible that loss of PAXX might reduce the fidelity of the end-joining products of cNHEJ, which in turn may cause abnormal gene expression and promote cancer development in the late stage of the lifespan." (PMID 35309348, 2022). "In addition, in view of the drug resistance of tumors with high expression of PAXX, whether the drug resistance can be reversed by finding suitable targets and designing combination drugs will play an important role in improving the efficiency of tumor treatment." (PMID 35309348, 2022). "Consistent with the Oncomine analysis, comparison of all available normal (n = 41) and tumor tissues (n = 469) revealed overexpression of XRCC6, XRCC5, PRKDC, XRCC4, and PAXX in tumors compared to normal tissues, while LIG4 and NHEJ1 displayed lower expression in the tumor tissues." (PMID 33195430, 2020). "However, analysis of 41 paired normal and tumor tissues revealed significant overexpression of only XRCC5, PRKDC, and PAXX genes in tumor tissues compared to the normal colon (respectively), while LIG4 and NHEJ1 still displayed reduced expression (respectively)." (PMID 33195430, 2020).
infection (2 papers, 2017 to 2023). The state of being infected such as from the introduction of a foreign agent such as serum, vaccine, antigenic substance or organism. "After 12 and 24 h of infection monomeric forms (represented by Q and S) were visible in both WT and PAXX−/− cells, and the relative levels of K to Q and S fragments was similar between genotypes." (PMID 29144403, 2017). "We observed that prior to infection PAXX is both nuclear and cytoplasmic but at both 8 and 16 h post-infection a large reduction in levels of nuclear PAXX was observed." (PMID 29144403, 2017). "In the absence of the HSV-1 glycoprotein gE this complex cannot form, so to visualise endogenous PAXX during infection U2OS cells were infected with a ΔgE YFP-VP26 HSV-1 virus." (PMID 29144403, 2017). "To complement the observations made with gene transcription, we also investigated the effect of PAXX on HSV-1 protein expression during infection." (PMID 29144403, 2017). "Samples were fractionated into nuclear and cytoplasmic compartments, and immunoblotting was performed to visualise PAXX levels in these compartments during infection." (PMID 29144403, 2017). "WT and PAXX−/− RPE-1 cells were infected at MOI 1, and protein was harvested at various times post-infection." (PMID 29144403, 2017). "WT and PAXX−/− RPE-1 cells were infected at MOI 4 with HSV-1, and viral and cellular DNA was isolated at various times post-infection." (PMID 29144403, 2017). "After eight and 12 h of infection, there were significantly more genomes per cell in WT RPE-1 cells than in PAXX−/− cells." (PMID 29144403, 2017). "Despite this specific reduction in nuclear PAXX, immunoblotting of whole cell lysates indicated that overall PAXX levels were not significantly reduced during infection." (PMID 29144403, 2017).
PAXX also shares sentences with these, for which no sentence is quoted: acute lymphocytic leukemia (1 paper); adenocarcinoma (1); colorectal cancer (1); leukemia (1); lymph node metastasis (1); mucinous adenocarcinoma (1); neural tumors (1); Werner syndrome (1).